IL33 (interleukin 33)
Diseases named in the same sentence as IL33 in open-access papers (continued):
Sharing a sentence is not in itself a finding about the gene and the disease.
pancreatic cancer (continued). "However, in pancreatic cancer patients high IL33 expression and high number of tumor-infiltrating ILC2s correlated with better survival." (PMID 32719677, 2020). "Moreover, Andersson and colleagues recently demonstrated that in mouse and human fibroblast-rich pancreatic cancers, genetic deletion of IL-33, ST2 or MMP-9 markedly blocked metastasis." (PMID 31231372, 2019). "IL-33 is expressed in the nucleus of pancreatic stellate cells (PSCs) that when activated, play a pivotal role in pancreatic fibrosis that is found in chronic pancreatitis and pancreatic cancer." (PMID 30205617, 2018). "Importantly, in pancreatic cancer, the anti-tumorigenic activity of IL-33 has been demonstrated through tumor cell-intrinsic downregulation of cellular proliferating proteins, such as CDK2 and CDK4, and upregulation of pro-apoptotic molecules, such as Bax and TRAIL." (PMID 34209038, 2021). "Thus, IL-33 acts as a chromatin-activated effector in neoplasia development of pancreatic cancer." (PMID 34023857, 2021). "Thus, the role of the IL-33/ST2L axis in regulating pancreatic cancer progression is unresolved." (PMID 32340025, 2020). "Our study reveals that tropisetron, a 5-HT3 receptor antagonist, blocks IL-33 expression by inhibiting IRF3 activation and effectively reduces chronic pancreatitis and prevents pancreatic cancer." (PMID 40647388, 2025). "Expression of IL33 and other IRF3 target genes, TNF, IL1B, and CXCL10, were highly upregulated in pancreatic cancer compared to the normal pancreas in a large collection of samples represented in TCGA and GTEx databases." (PMID 38816352, 2024). "In contrast, tropisetron treatment did not influence the pancreatic tumor development in caerulein-treated KPC mice lacking Il33 expression (Il33KO KPC)." (PMID 40647388, 2025). "However, intra-tumoral fungi mediate IL-33 secretion by PDAC cells, and genetic defects in IL-33 or antifungal treatment inhibit pancreatic tumor growth and support prolonged mouse survival." (PMID 39309440, 2024). "In pancreatic cancer models, CAF-secreted IL-33 commits macrophage M2 polarization." (PMID 38303024, 2024). "Moreover, genetic deletion of IL-33, ST2, or MMP-9 evidently inhibited metastasis in fibroblast-rich human and mouse pancreatic cancers." (PMID 34209038, 2021). "Therefore, to find additional markers for the differential diagnosis between type 1 AIP and pancreatic cancer (perhaps IFN-α and IL-33 serum levels) is essential, and will be the focus of our next study." (PMID 32938972, 2020). "This is supported by the previous finding that IL-33 ligating to its receptor could inhibit GSK-3β that normally regulates the proliferation and survival of pancreatic cancer cells 34, finally leading to attenuation of cancer progression." (PMID 33046978, 2020). "The role of PD-1 in exogenous IL-33-driven ILC-2 antitumor responses has been reported in models of pancreatic cancer and in metastatic melanoma, but whether PD-1 function is relevant in the absence of the addition of exogenous IL-33 is unknown." (PMID 37098069, 2023). "Tissue-specific IL-33-activated ILC2s may exert protective anti-tumor immunity in orthotopic, but not subcutaneous, implants of pancreatic cancer." (PMID 35658010, 2022). "Given the widespread expression and multiple downstream functions of IL-33 as well as the difficulty in identifying pancreatic cancer initiation clinically, IL-33 may not be a direct target for the prevention or early diagnosis of pancreatic cancer." (PMID 34023857, 2021). "In animal study, they found that interleukin-33 (IL33) activates tumor ILC2s and CD8+ T cells to limit pancreas-specific tumor growth in orthotopic pancreatic tumors but not heterotopic skin tumors." (PMID 34884642, 2021).
pancreatic cancer (continued). "Our results show that P2X7R (~20-fold), its key inflammasome components: caspase-1 (15-fold), IL-1β (~45-fold), and in addition to (data not shown) IL-18 (~35-fold), IL-33 (~93 folds), TNF-α (~13-fold) and COX-2 (~41-fold) are increased in pancreatic tumors compared to normal pancreas." (PMID 29228654, 2017).
airway hyperresponsiveness (43 papers, 2012 to 2026). "RV infection of 6 day-old mice, but not mature mice, induces type airway inflammation, mucous metaplasia and airways hyperresponsiveness which is associated with expansion of IL-13-producing ILC2s and dependent on the innate cytokines IL-25, IL-33 and TSLP." (PMID 41573550, 2025). "Using quantitative morphometry of the airway wall, it has been demonstrated that IL-33 causes a shift in mast cells from the submucosa to the airway epithelium associated with type 2 inflammation and airway hyperresponsiveness (AHR)." (PMID 33445787, 2021). "In conclusions, we observed that colonization with Gram negative respiratory pathogens is associated with an increased airway hyperresponsiveness in our cohort of asthmatic children and induced IL-33 in the airways." (PMID 28262704, 2017). "RV infection of 6 day-old mice, but not mature mice, induces type 2 airway inflammation, mucous metaplasia and airways hyperresponsiveness which is associated with expansion of IL-13-producing type 2 innate lymphoid cells (ILC2s) and dependent on the innate cytokines IL-25, IL-33 and TSLP." (PMID 41573550, 2025). "Studies indicate that PFAS exposure can activate inflammasomes in bronchial epithelial cells, leading to the release of pro-inflammatory cytokines (IL-1β, IL-18, and IL-33) and airway hyperresponsiveness." (PMID 41150549, 2025). "We have shown that RV1B infection of 6-day-old mice induces mucous metaplasia and airway hyperresponsiveness that is associated with ILC2 expansion and dependent on IL-13, IL-25, IL-33, and TSLP." (PMID 38061015, 2024). "Previous animal research has demonstrated that O3 exposure can increase the production of Th2 cytokines, eosinophilic airway inflammation, and IL-33 airway hyperresponsiveness in a dose-dependent manner." (PMID 37999544, 2023). "The results showed that vaccination induced high titers of specific anti-IL-33 IgG antibodies, suppressed airway hyperresponsiveness, and attenuated elevated eosinophil counts in bronchoalveolar lavage fluid." (PMID 38082335, 2023). "Researchers have previously reported that increased IL-33 expression in ASM bundles of asthmatic airway is correlated with airway hyperresponsiveness." (PMID 35547213, 2022). "We did this by stimulating airway fibroblasts with a 1 ng/ml dose of recombinant IL-1α, IL-1β or IL-33 for 24 hours and then assessed the release of inflammatory mediators known to be involved in chronic inflammation, and airway hyperresponsiveness in asthma." (PMID 32457454, 2020). "In another study a decrease in eosinophil count in BAL fluid and reduced airway hyperresponsiveness to methacholine was observed following anti-IL-33 antibody and sST2 receptors treatment." (PMID 31057533, 2019). "The data indicate that the interleukin-33 /ST2 pathway contributes to ozone-induced airway hyperresponsiveness in male mice and suggest that the role of interleukin-33 is mediated at the level of the gut microbiome." (PMID 31455422, 2019). "It has been shown that through the activation of IL-5 and IL-13 secretion, IL-33 promotes airway hyperresponsiveness." (PMID 31057533, 2019). "Vaccination against IL-33 induced high titers of specific anti-IL-33 IgG antibodies that inhibited HDM-induced airway hyperresponsiveness (AHR) in the conducting airways and tissue damping." (PMID 26214807, 2015). "Although anti-IL-33 treatment has been shown to attenuate deleterious type 2 memory responses during rhinovirus infection, thereby reducing airway hyperresponsiveness, the specific mechanisms by which IL-33 regulates CD4+ T cells in SARS-CoV-2 infection remain to be explored." (PMID 36362440, 2022). "In addition, it also induced eosinophilic inflammation, the production of IL-4, IL-5, IL-13, and IL-33 in bronchoalveolar lavage fluid, and airway hyperresponsiveness." (PMID 34079051, 2021).
airway hyperresponsiveness (continued). "The purpose of this study was to determine whether there were sex differences in the role of interleukin-33 in ozone-induced airway hyperresponsiveness and to examine the role of the microbiome in these events." (PMID 31455422, 2019). "In the present study, we provide evidence that IL-33 exacerbates antigen-induced asthmatic responses, including airway hyperresponsiveness, inflammation and remodeling, mast cell activation, production of IgE and cytokines including IL-4, IL-5 and IL-13, and accumulation of pulmonary ILC2s." (PMID 28652606, 2017). "Then airway hyperresponsiveness (AHR), eosinophil percentage, levels of interleukin (IL)‐33, IL‐25, IL‐13, IL‐5, IL‐4, total and ovalbumin (OVA)‐specific immunoglobulin (Ig)E, and lung histopathology were evaluated." (PMID 38664220, 2024). "Administration of anti‐IL‐23 antibody led to decreased airway hyperresponsiveness, eosinophils, and activation of dendritic cells, reduced populations of Th2 Th17, ILC2, the level of IL‐33 and granulocyte‐macrophage colony‐stimulating factor (GM‐CSF)." (PMID 35801505, 2022). "Studies showed that ST2-/- mice prompted by allergen-induced airway hyperresponsiveness (AHR) presented reduced inflammation in the peripheral airways, suggesting that IL-33/ST2 signaling is important for the influx of cells into the airways." (PMID 34324507, 2021). "This is especially relevant when considering that elevations of circulating IL-33 on HDM stimulation have been reported in mouse models, with attenuated HDM-induced airway hyperresponsiveness in IL1RL1-KO mice." (PMID 32324168, 2020). "In neonatal mice A alternata exposure induced higher serum IgE levels, pulmonary IL-33 levels, and IL-13+ innate lymphoid cell (ILC) and TH2 cell numbers but similar airway hyperresponsiveness (AHR) compared with those after house dust mite exposure." (PMID 25746970, 2015). "This alteration may lead to an increased release of pro-inflammatory cytokines, such as IL-33 and TNF-α, thereby exacerbating inflammation and airway hyperresponsiveness." (PMID 40949724, 2025). "We have shown that rhinovirus A1B (RV1B) infection of 6-day-old mice, but not mature mice, induces mucous metaplasia and airway hyperresponsiveness that is associated with ILC2 expansion and dependent on IL-13, IL-25, IL-33, and TSLP." (PMID 38061015, 2024). "Our data show that Miro1 suppresses epithelial induction and maintenance of the inflammatory response to allergen, as Miro1 deletion modestly induces increases in pro-inflammatory signaling, specifically IL-6, IL-33, CCL20 and eotaxin levels, tissue reorganization, and airway hyperresponsiveness." (PMID 37377691, 2023). "Several cytokines are now known to be key regulators of events that can lead to the development of airway hyperresponsiveness (AHR) and chronic inflammation, including IL-18, IL-25, IL-33 and thymic stromal lymphopoietin (TSLP), all of which are released by epithelial cells." (PMID 26214807, 2015).
influenza infection (43 papers, 2012 to 2025). "In support of this association, nasally administered IL-33 has been reported to enhance the induction of mucosal IgA following inactivated influenza vaccination in mice." (PMID 38052824, 2023). "In vitro study confirmed that blockade of IL-33 is correlated with a worse outcome after influenza infection and, moreover, that a restoration of its levels is linked with an improvement of final outcome." (PMID 35327516, 2022). "$$$$Basal epithelial stem cells (basal ESCs), a newly distinguished AQP3+ IL‐33+ basal cell subset, participated in bronchiolar–alveolar remodeling in response to influenza infection and expanded by crossing a cell‐growth and survival checkpoint linked to the nuclear‐localized alarmin IL‐33." (PMID 41318981, 2025). "Both interleukin-10 (Il10), a regulatory cytokine associated with decreased immunopathology during influenza infection, and interleukin-1 receptor like 1 (Il1rl1), the receptor for the alarmin IL-33 that alerts of epithelial trauma, were down-regulated in obese ferrets compared to control." (PMID 38728395, 2024). "Specifically, two classical immune-related pathways, the “Role of Hypercytokinemia/hyperchemokinemia in the Pathogenesis of Influenza” and the “IL-33 Signalling Pathway”, are activated in the CRP 1–3 group vs. >3." (PMID 39271754, 2025). "Airway ILCs have been reported to protect against influenza-induced lung damage, including epithelial integrity and airway remodeling, in response to influenza infection, which is mediated by IL-33 and AREG." (PMID 38684766, 2024). "It is plausible that O3-induced IL-33 in the cytokine milieu is involved in an immune crosstalk assisting human defense against influenza." (PMID 38704386, 2024). "Intranasal administration of IL-33 promoted vaccine-induced protection in an influenza mouse model, which was mediated by ILC2s." (PMID 38684766, 2024). "For instance, IL-33 can mediate lung tissue repair by inducing the activation of Tregs and ILC2s after influenza infection." (PMID 37240045, 2023). "Conversely, blocking the IL-33/IL-33R signaling pathway or the use of anti-CD90 monoclonal antibodies to block ILC2 expansion protected mice from the influenza-induced AHR, thereby proving an essential role of ILC2s in mediating airway inflammation." (PMID 38179045, 2023). "Another preclinical study found that infection of mice with influenza activates the IL-33/IL-13 axis, thus inducing airway inflammation mainly upon activation of macrophages and neutrophils." (PMID 37240045, 2023). "Taking their results together, the authors showed that exogenous IL-33 exhibits an antiviral effect in the lung against influenza infection through a reinforced antiviral immunity, resulting in increased survival and viral clearance." (PMID 35327516, 2022). "Supporting those observations, a recent study using a murine model showed that IL-33 suppressed innate antiviral responses and adaptive Th1 responses in influenza-induced exacerbations, which enhanced asthmatic airway inflammation." (PMID 36077310, 2022). "While the links between IL-17A and IL-33 pathways are unclear during influenza infection, they play an important role in type-2 immunity and mediating infection responses in the young." (PMID 36061377, 2022). "Based on these findings, in influenza infection, IL-33 seems to act as a protective factor, inducing better viral clearance and promoting tissue repair and lung integrity." (PMID 35327516, 2022). "There is contradicting evidence on how IL-17A and influenza induces IL-33 production and the downstream effects triggered for tissue repair and remodeling." (PMID 36061377, 2022). "On tissue damage, IL-33 is released by necrotic cells which promotes ILC2 accumulation as seen in the lungs of influenza-infected mice." (PMID 33936115, 2021).
influenza infection (continued). "For example, IL-33 receptor ST2 signaling drives type 2 immune pathology during respiratory viral infection; IL-33 mediates influenza airway pathology by eliciting IL-13 production by innate lymphoid cells." (PMID 33857419, 2021). "We found that the protective ability of an influenza vaccine administered with HP-β-CD against a lethal dose of PR8 influenza virus infection was decreased in Il33−/− mice." (PMID 32210964, 2020). "This was correlated with early high IL-33 that persisted throughout influenza infection, and later induction of myriad pro-inflammatory mediators including KC, TNFα, IL-6, IL-12p40, IL-17A, CCL2, CCL20, and RANTES." (PMID 33101299, 2020). "Mice with house dust mite (HDM)-induced allergic airway disease infected with influenza and primary bronchial epithelial cells from patients with mild, atopic asthma infected with RV produce IL-33 that subsequently suppresses production of type I IFNs." (PMID 33101299, 2020). "Previous studies have reported that intratracheal administration of exogenous IL-33 is effective in protecting against influenza infection." (PMID 32210964, 2020). "To confirm the protective role of IL-33 during influenza infection, we immunized Il33+/− or Il33−/− mice with the influenza split vaccine plus HP-β-CD following PR8 infection." (PMID 32210964, 2020). "The authors found a similar correlation of IL-17, IL-33, and amphiregulin in the nasal wash of human infants infected with influenza, identifying an axis of IL-17 production from γδ-T cells in the production of IL-33 for ILC2 repair responses in the lung." (PMID 31354734, 2019). "Our findings suggest an antiviral effect of exogenous IL-33 in the lung against influenza infection." (PMID 31509992, 2019). "In mice following challenge with influenza virus, release of IL-33 corresponded with elevated IL-5 production by ILC2s and the recruitment of eosinophils to the lung during the recovery phase of influenza infection." (PMID 31354734, 2019). "To date, the mechanism by which interleukin (IL)-33 modulates the antiviral immune response post-influenza infection is unclear." (PMID 31509992, 2019). "In this study, we show that exogenous IL-33 affected mortality against influenza infection by increasing dendritic cell (DC) recruitment, pro-inflammatory cytokine secretion, and cytotoxic T-cell responses in a local microenvironment." (PMID 31509992, 2019). "To determine the effect of exogenous IL-33 on antiviral immunity against influenza infection, we examined the results of intranasal PR8 infection following daily intranasal injections of rIL-33 for five days." (PMID 31509992, 2019). "To determine the effect of endogenous IL-33 on antiviral immunity against influenza infection, we examined the outcomes of intranasal PR8 infection in IL-33-deficient mice." (PMID 31509992, 2019). "Intriguingly, IL-17 production from γδ-T cells was shown during neonatal influenza to augment IL-33 production from the mucosa, generating a type 2 response and the production of amphiregulin by ILC2s." (PMID 31354734, 2019). "In comparison, IL-17A-producing γδT cells in the lung can upregulate expression of IL-33 and amphiregulin, thereby promoting lung repair following influenza infection." (PMID 31337278, 2019). "The rapid secretion of IL-17A by γδ T cells from neonatal mice promotes AECs to produce IL-33, protecting neonates from severe influenza." (PMID 31612153, 2019). "IL-33 is produced early after influenza infection, and was therefore tested for its ability to enhance the lung MCp population." (PMID 30337928, 2018). "One such molecule is IL-33, which is released from damaged airway epithelial cells and alveolar macrophages early upon influenza infection." (PMID 30337928, 2018). "As L. paracasei feeding, before or after influenza infection, induced secretion of IL-1β and IL-33, we focused our attention on the presence of cytokine-expressing ILCs and T cells." (PMID 28931041, 2017).